RRP1B (ribosomal RNA processing 1B)
Description:
Positively regulates DNA damage-induced apoptosis by acting as a transcriptional coactivator of proapoptotic target genes of the transcriptional activator E2F1. Likely to play a role in ribosome biogenesis by targeting serine/threonine protein phosphatase PP1 to the nucleolus. Involved in regulation of mRNA splicing (By similarity). Inhibits SIPA1 GTPase activity (By similarity). Involved in regulating expression of extracellular matrix genes (By similarity). Associates with chromatin and may play a role in modulating chromatin structure. (Microbial infection) Following influenza A virus (IAV) infection, promotes viral mRNA transcription by facilitating the binding of IAV RNA-directed RNA polymerase to capped mRNA.
Synonyms: KIAA0179; Nnp1; RRP1; PPP1R136; NNP1L
Tractability: PROTAC: ubiquitination databases record sites on it; its protein half-life has been measured.
Gene: Protein-coding gene on chromosome 21 (43,659,560 to 43,696,079, forward strand). Ensembl gene ENSG00000160208.
Subcellular location: Nucleus, nucleolus; Nucleus, nucleoplasm; Chromosome
Subcellular location (Human Protein Atlas): Mitotic chromosome; Nucleoli; Nucleoli rim; Nucleoplasm
Gene Ontology:
Molecular function: protein binding; RNA binding; transcription coactivator activity
Biological process: cellular response to virus; host-mediated activation of viral transcription; positive regulation of apoptotic process; positive regulation of transcription by RNA polymerase II; negative regulation of GTPase activity; regulation of RNA splicing; regulation of transcription by RNA polymerase II; rRNA processing
Cellular component: chromosome; cytosol; granular component; nucleolus; nucleoplasm; nucleus; euchromatin; heterochromatin; preribosome, small subunit precursor
Genetic constraint (gnomAD): Loss-of-function variants: 48 observed, 63.43 expected, observed/expected ratio (o/e) 0.76, 90% interval 0.6 to 0.96. The upper end of that interval is the gene's LOEUF score, 0.96, which puts it in group 4 of 6, group 1 being the genes least tolerant of losing a copy. Missense variants: 768 observed, 875.27 expected, observed/expected ratio (o/e) 0.88, 90% interval 0.83 to 0.93. Synonymous variants: 334 observed, 335.22 expected, observed/expected ratio (o/e) 1, 90% interval 0.91 to 1.09.
Homologues: Orthologues: chimpanzee RRP1B (99% identical), macaque RRP1B (96% identical), dog RRP1B (70% identical), rat Rrp1b (63% identical), guinea pig RRP1B (61% identical), mouse Rrp1b (61% identical), pig RRP1B (59% identical), rabbit RRP1B (56% identical), tropical clawed frog rrp1b (34% identical), zebrafish rrp1 (29% identical), Drosophila melanogaster Nnp-1 (20% identical), Caenorhabditis elegans rrp-1 (14% identical). Paralogues in human: RRP1 (28% identical).